RNF31 (ring finger protein 31)
Description:
E3 ubiquitin-protein ligase component of the LUBAC complex which conjugates linear ('Met-1'-linked) polyubiquitin chains to substrates and plays a key role in NF-kappa-B activation and regulation of inflammation. LUBAC conjugates linear polyubiquitin to IKBKG and RIPK1 and is involved in activation of the canonical NF-kappa-B and the JNK signaling pathways. Linear ubiquitination mediated by the LUBAC complex interferes with TNF-induced cell death and thereby prevents inflammation. LUBAC is recruited to the TNF-R1 signaling complex (TNF-RSC) following polyubiquitination of TNF-RSC components by BIRC2 and/or BIRC3 and to conjugate linear polyubiquitin to IKBKG and possibly other components contributing to the stability of the complex. The LUBAC complex is also involved in innate immunity by conjugating linear polyubiquitin chains at the surface of bacteria invading the cytosol to form the ubiquitin coat surrounding bacteria. LUBAC is not able to initiate formation of the bacterial ubiquitin coat, and can only promote formation of linear polyubiquitins on pre-existing ubiquitin. Recruited to the surface of bacteria by RNF213, which initiates the bacterial ubiquitin coat. The bacterial ubiquitin coat acts as an 'eat-me' signal for xenophagy and promotes NF-kappa-B activation. Together with OTULIN, the LUBAC complex regulates the canonical Wnt signaling during angiogenesis. RNF31 is required for linear ubiquitination of BCL10, thereby promoting TCR-induced NF-kappa-B activation. Binds polyubiquitin of different linkage types.
Synonyms: HOIP; ZIBRA; FLJ10111; FLJ23501; Paul; IMD115
Tractability: Small molecule: a structure with a bound ligand is known. PROTAC: UniProt records ubiquitination sites on it; ubiquitination databases record sites on it; its protein half-life has been measured; a small molecule that binds it is known.
Target class: Enzyme; Transferase
Gene: Protein-coding gene on chromosome 14 (24,146,683 to 24,160,660, forward strand). Ensembl gene ENSG00000092098.
Subcellular location: Cytoplasm
Subcellular location (Human Protein Atlas): Cytosol
Pathways (Reactome):
Signal Transduction: Regulation of TNFR1 signaling; TNFR1-induced NF-kappa-B signaling pathway; TNFR1-induced proapoptotic signaling
Gene Ontology:
Molecular function: identical protein binding; protein binding; ubiquitin binding; ubiquitin protein ligase activity; ubiquitin protein ligase binding; ubiquitin-protein transferase activity; K48-linked polyubiquitin modification-dependent protein binding; K63-linked polyubiquitin modification-dependent protein binding; linear polyubiquitin binding; zinc ion binding
Biological process: defense response to bacterium; positive regulation of canonical NF-kappaB signal transduction; positive regulation of establishment of protein localization to mitochondrion; positive regulation of xenophagy; protein linear polyubiquitination; protein polyubiquitination; T cell receptor signaling pathway; CD40 signaling pathway; cell surface receptor signaling pathway; protein ubiquitination
Cellular component: LUBAC complex; CD40 receptor complex; cytoplasm; cytoplasmic side of plasma membrane; cytosol
Genetic constraint (gnomAD): Loss-of-function variants: 38 observed, 134.67 expected, observed/expected ratio (o/e) 0.28, 90% interval 0.22 to 0.37. The upper end of that interval is the gene's LOEUF score, 0.37, which puts it in group 1 of 6, group 1 being the genes least tolerant of losing a copy. Missense variants: 1,118 observed, 1,432.9 expected, observed/expected ratio (o/e) 0.78, 90% interval 0.74 to 0.82. Synonymous variants: 582 observed, 566.98 expected, observed/expected ratio (o/e) 1.03, 90% interval 0.96 to 1.1.
Gene-disease validity (ClinGen):
ClinGen rates the evidence that RNF31 causes each of these diseases.
immunodeficiency 115 with autoinflammation (autosomal recessive): Moderate.
Homologues: Orthologues: chimpanzee RNF31 (99% identical), macaque RNF31 (98% identical), pig RNF31 (92% identical), dog RNF31 (92% identical), guinea pig RNF31 (88% identical), mouse Rnf31 (86% identical), rat Rnf31 (86% identical), rabbit RNF31 (79% identical), tropical clawed frog rnf31 (51% identical), Drosophila melanogaster LUBEL (30% identical).
Diseases named in the same sentence as RNF31 in open-access papers:
RNF31 is named in the same sentence as 105 diseases in open-access papers, as found by Europe PMC text mining. Sharing a sentence is not in itself a finding about the gene and the disease. The quoted sentences say what the papers report.
Immunodeficiency (24 papers, 2016 to 2025). Failure of the immune system to protect the body adequately from infection, due to the absence or insufficiency of some component process or substance. "Biallelic HOIL-1L (RBCK1) or HOIP (RNF31) variants result in autoinflammation with immunodeficiency." (PMID 38652464, 2024). "Mutations in RBCK, encoding HOIL-1L, and RNF31, encoding HOIP, are found in patients suffering from autoinflammation and immunodeficiency." (PMID 33923887, 2021). "RNF31 is also observed to contribute to inborn human immunity disorders, in which RNF31 missense mutation at PUB domain gives rise to the de-stabilized LUBAC complex and subsequently causes the auto-inflammation and immunodeficiency." (PMID 27460922, 2016). "Mutations in RNF31 may cause immunodeficiency, autoinflammation, amylopectinosis, and lymphangiectasia." (PMID 37273692, 2023). "Similarly, the association of autoinflammatory disease with both increased and decreased linear ubiquitination and the coexistence of immunodeficiency and autoinflammation in RNF31- and RBCK1-deficient patients seem contradictory." (PMID 32687504, 2020). "Fibroblasts from patients multi-organ autoinflammation, immunodeficiency, and amylopectinosis due to loss of function mutations in RBCK1 and RNF31 exhibited diminished IL1B- and TNF-induced NFκB activation yet monocytes were hyper-responsive to IL1B." (PMID 32687504, 2020). "Genetically determined deficiencies in RNF31 and RBCK1 cause immune deficiency, autoinflammatory disease, and glycogen storage disease in human patients, whereas absence of OTULIN has been reported in six patients with an autoinflammatory syndrome." (PMID 32687504, 2020). "Biallelic LoF mutations in two of the LUBAC component: HOIL-1 (heme-oxidized IRP2 ubiquitin ligase 1; RBCK1) or HOIP (HOIL-1 interacting protein; RNF31), cause LUBAC deficiency, an autosomal recessive disease characterized by severe immunodeficiency, recurrent fever, and polyglucosan myopathy." (PMID 34163478, 2021). "In this regard, humans with a genetic defect in RNF31 (coding for HOIP) or RBCK1 (coding for HOIL1) developed autoinflammation and immunodeficiency, which overlap with the phenotype observed in the SHARPIN-deficient mice." (PMID 31457011, 2019).
breast carcinoma (19 papers, 2015 to 2024). "Since RNF31 was initially found in breast cancer cells, it has been shown to be overexpressed in many tumors and associated with tumorigenesis, such as in breast cancer, pituitary adenoma and prostate cancer." (PMID 33824292, 2021). "Furthermore, RNF31 plays an important role in various solid tumors, such as prostate, gastric, colon, and breast cancers, in which its levels are elevated, in association with a dismal prognosis, by multiple mechanisms." (PMID 35869046, 2022). "For example, RNF31 could associate with ERα, mono-ubiquitinate ERα and promote breast cancer proliferation." (PMID 32973333, 2020). "Inhibition of RNF31 (either genetically or pharmacologically) greatly increases the sensitivity of melanoma, breast cancer, and colorectal cancer cells to NK and CD8 + T cells." (PMID 37117215, 2023). "Here, we reported an important LUBAC component RNF31 in modulating breast cancer progression and Hippo signaling, which provide novel knowledge in crosstalk between LUBAC complex and Hippo pathway." (PMID 36581998, 2022). "RNF31 was originally cloned from breast cancer cells and was identified to be highly expressed in breast cancer tissues compared to the adjacent normal tissues." (PMID 35216622, 2022). "For instance, in breast cancer, RNF31 interacts with ERα, supporting its mono-ubiquitination and enhancing Erα stability, thereby promoting the growth of breast cancer." (PMID 35869046, 2022). "For example, in breast cancer, RNF31 supports ERα mono-ubiquitination and enhances its stability, thereby promoting breast cancer proliferation." (PMID 35869046, 2022). "RNF31 was originally cloned from breast cancer cells based on its higher mRNA expression compared to normal breast cell lines." (PMID 29763465, 2018). "We have recently reported that RNF31 mRNA expression is significantly higher in breast cancer samples compared to adjacent tissue in an Iranian cross sectional study." (PMID 29763465, 2018). "As one of the RNF family member, RNF31 (other names: HOIP; ZIBRA) was first cloned from breast cancer cell line and was identified as a classical component in linear ubiquitin assembly complex (LUBAC) to facilitate NFκB signaling transduction." (PMID 27460922, 2016). "Here we want to review the current knowledge about RNF31 as an ubiquitin ligase in breast cancer cell progression." (PMID 27460922, 2016). "Analysis of breast cancer samples reveals that RNF31 is highly expressed in breast tumors compared with adjacent tissues, while RNF31 expression is correlated with ERα target genes both in cell line and in clinical samples." (PMID 27460922, 2016).
breast carcinoma (continued). "This review highlights recent discoveries on RNF31 functions in nuclear factor modifications, breast cancer progression and possible therapeutic inhibitors targeting RNF31." (PMID 27460922, 2016). "Besides, RNF31 was also found to induce the mono-ubiquitination of ER alpha and breast cancer progression." (PMID 36280829, 2022). "Recent studies have shown that RNF31 may function as a breast cancer oncogene by any of the following mechanisms." (PMID 35216622, 2022). "In line with this, we have also recently reported that RNF31 is significantly overexpressed in breast cancer tumors compared to adjacent non-tumor tissues and can facilitate ERalpha-dependent proliferation in breast cancer cell lines through monoubiquitination of ERalpha protein." (PMID 29763465, 2018). "In addition, we have recently reported that RNF31 stabilizes ERalpha via a monoubiquitination mechanism, and facilitates ERalpha-dependent proliferation in breast cancer cell lines." (PMID 29763465, 2018). "As a group of ubiquitin ligases have been shown to facilitate estrogen signaling in breast cancer cell, such as BRCA1, CHIP and RNF31, it may suggest ER signaling and turnover is tightly linked to ubiquitin-proteasome system." (PMID 29100376, 2017). "RNF31 and ERα association mainly occurs in the cytosol and activates the non-genomic mechanism, by which RNF31 via stabilizing ERα levels, controls the transcription of oestrogen-dependent genes linked to breast cancer cell proliferation." (PMID 27884978, 2016). "The knowledge of RNF31 and its role in breast cancer is still very limited." (PMID 27460922, 2016). "Besides, in RNF31 knocking down background, RNF31 overexpression could decrease the proportion of CD44+/CD24- breast cancer cells." (PMID 36581998, 2022). "However, our new finding of the elevated RNF31 protein expression in ERα-negative tumors could also indicate an ERalpha-independent role of RNF31 in breast cancer." (PMID 29763465, 2018). "RNF31 (RING finger protein 31; HOIP; ZEBRA) was firstly discovered in 2004 from breast cancer MCF-7 cells, which contained several functional domains including ZNF-RBZ domain, UBA (Ubiquitin binding associated) domain and RBR (RING-IBR-RING) domain." (PMID 36581998, 2022). "For example, RNF31 and RNF8 function ubiquitin ligases, which promote the monoubiquitination of ERα, enhance ERα protein stability and estrogen signaling activity in breast cancer cancers." (PMID 34094957, 2021). "While ERalpha has already been well documented to play an important role in the etiology and progression of breast cancer, RBCK1, RNF31 and SHARPIN has recently emerged as potential new players in tumorigenesis." (PMID 29763465, 2018). "Ring finger protein 31 (RNF31, also named HOIP), Ran Bp-type and C3HC4-type zinc finger-containing protein 1 (RBCK1), and Ariadne homolog 1 (ARIH1) are members of RBR E3 ligases that are up-regulated in breast cancer." (PMID 35216622, 2022). "Follow-up of patients and evaluation of the expression of RBCK1, RNF31 and SHARPIN with tumor recurrence and overall survival of patients may further shed lights on the prognostic role of this complex on breast cancer." (PMID 29763465, 2018).
breast carcinoma (continued). "We have already reported that RNF31 mRNA levels are higher in breast cancer samples compared to adjacent non-tumor tissue." (PMID 29763465, 2018). "Interestingly, RNF31 was elevated in ER+ breast cancer, but its expression was decreased in TNBC compared with normal breast tissue in TCGA database, which consistent with our previous study." (PMID 36581998, 2022). "Collectively, our findings indicate that up-regulated mRNA expression of RNF31, RBCK1 and SHARPIN could potentially be diagnostic biomarkers of breast cancer and RNF31 might be a drug target for ERalpha-negative breast cancers." (PMID 29763465, 2018). "Although our previous study showed another component-RNF31 could also promote ERα mono-ubiquitination in breast cancer cells, the RNF31 modification effect on ERα is not dependent on the Ubiquitin-associated domain (UBA), which is necessary for LUBAC formation." (PMID 29100376, 2017).
viral infection (6 papers, 2020 to 2025). "To clarify the expression of RNF31 in normal liver, we identified within our cohort HCC cases that had no clinically relevant underlying disease in the background liver, such as cirrhosis, chronic inflammation, fibrosis, or viral infection." (PMID 38172174, 2024).
colon carcinoma (4 papers, 2016 to 2025). "Small molecule RNF31 inhibitors sensitize colon cancer organoids to TNF-mediated death." (PMID 37117215, 2023). "In addition, taraxasterol (50 μg/mL) significantly induces excessive autophagy to inhibit the proliferation of human colon cancer HCT116 and SW480 cells, in which taraxasterol promotes the degradation of pro-cancer gene ring finger protein 31 (RNF31)." (PMID 41374059, 2025). "Moreover, previous studies have revealed a markedly negative correlation between RNF31 expression and survival time in a variety of cancer types, such as prostate, breast, gastric, and colon cancers." (PMID 35869046, 2022).
hepatocellular carcinoma (3 papers, 2017 to 2024). A malignant tumor that arises from hepatocytes. "We aimed to clarify the role of RNF31 in the pathogenesis of hepatocellular carcinoma (HCC) and its relevance as a therapeutic target." (PMID 38172174, 2024).
lymphangiectasia (3 papers, 2019 to 2021). "The clinical and histological absence of lymphangiectasia in our patient is noteworthy, because the vessel formation abnormality has been observed in the previous HOIP-deficient patient as well as in Rnf31-knock out mice." (PMID 30936877, 2019).
lymphoma (3 papers, 2015 to 2021). A malignant (clonal) proliferation of B- lymphocytes or T- lymphocytes which involves the lymph nodes, bone marrow and/or extranodal sites. "A lymphoma study showed that the blocking peptide targeting UBL domain of RNF31 significantly inhibited lymphoma proliferation." (PMID 27460922, 2016). "Currently, RNF31 was found to facilities lymphoma growth through NFκB pathway." (PMID 27460922, 2016).
prostate carcinoma (3 papers, 2019 to 2023). A carcinoma that arises from epithelial cells of the prostate gland. "RNF31 has been reported to be significantly increased in prostate cancer (PCa) and has been associated with some malignant behaviors, suggesting that RNF31 plays an oncogenic role in PCa progression." (PMID 37117215, 2023). "In addition, miR-503 was downregulated in prostate cancer tissues while acting as an inhibitor of proliferation and metastasis of prostate cancer cells by targeting RNF31." (PMID 33817293, 2021).
Adrenocortical Cancer (2 papers, 2012 to 2023). "We found a significant association between RNF31 expression and different molecular subtypes of adrenocortical carcinoma (ACC), BRCA, COAD, ESCA, brain lower grade glioma (LGG), OV, PCPG, PRAD, STAD and UCEC." (PMID 37117215, 2023). "In an effort to elucidate the roles of SF-1 and RNF31 in adrenal steroidogenesis and adrenocortical carcinoma on a genome-wide level, we performed siRNA-mediated knockdown of SF-1 or RNF31 ± cAMP in the adrenocortical carcinoma cell line NCI-H295R." (PMID 22427816, 2012).
breast tumors (2 papers, 2016 to 2018). "We compared RNF31, RBCK1 and SHARPIN mRNA and protein expression in a subset of breast tumors." (PMID 29763465, 2018). "Correlation of ERalpha, RBCK1, RNF31 and SHARPIN mRNA expression levels in breast tumors." (PMID 29763465, 2018).
liver cirrhosis (2 papers, 2022 to 2024). "However, in our cohort, RNF31 expression was not correlated with viral hepatitis or liver cirrhosis." (PMID 38172174, 2024). "Because RNF31 plays an important role in inflammatory signaling as a component of LUBAC, we initially expected that RNF31 could be related to an inflammatory background, such as liver cirrhosis or chronic viral infections." (PMID 38172174, 2024). "However, age, sex, tumor size, differentiation, alpha-fetoprotein, HBV DNA, and liver cirrhosis were not significantly correlated with RNF31 expression." (PMID 35869046, 2022).
melanoma (2 papers, 2022 to 2025). A malignant, usually aggressive tumor composed of atypical, neoplastic melanocytes. "To further elucidate the essential recruitment events within the TNFR1 complex that prevent T cell-mediated killing in tumor cells, we examined the TNFR1 complex composition in melanoma cells with a knockout mutation in RNF31." (PMID 41315176, 2025). "We further show that TNF is sufficient to induce apoptosis in Rnf31 deficient pancreatic cancer cells, in contrast to B16 melanoma cells where IFNɣ is required for TNF-induced apoptosis after Rnf31 disruption." (PMID 35379808, 2022).